NFATC2 (nuclear factor of activated T cells 2)
Diseases named in the same sentence as NFATC2 in open-access papers (continued):
Sharing a sentence is not in itself a finding about the gene and the disease.
asthma (4 papers, 2020 to 2025). "A previous study demonstrated that the number of T regulatory cells was increased in Nfatc2-deficient mice, inducing immunosuppression to control experimental asthma caused by allergens." (PMID 34285702, 2021). "NFATc2 mRNA showed a direct correlation with eosinophils both in controls and asthma, indicating that NFATc1 is associated with lymphocytes and not eosinophils in asthma." (PMID 33079489, 2020). "We also recently reported that the NFAT‐interacting protein (NIP)‐45, which induced IL‐4 by potentiating NFATc2, is induced in preschool children with asthma and NIP45 deficient mice have less airway eosinophilia." (PMID 33079489, 2020). "We next asked if NFATc2 would correlate with eosinophils in asthma as NFATc2 was associated with a Th2 trait." (PMID 33079489, 2020). "In patients with asthma, NFATC2 is associated with peripheral eosinophilia." (PMID 40108736, 2025). "Here, we sought to investigate the role of NFATc1 and NFATc2 in different cohorts of asthmatic and control children and adults to better understand the distinct role of these two transcription factors and their association with different forms of asthma." (PMID 33079489, 2020). "Two transcription factors, forkhead box Q1 (Foxq1) and nuclear factor of activated T cells 2 (Nfatc2), served important regulatory roles in asthma." (PMID 34285702, 2021). "Consistently, in the AGENDAs cohort, NFATc2 mRNA correlated with peripheral blood eosinophils in asthma." (PMID 33079489, 2020). "We next analyzed NFATc1 and NFATc2 mRNA in the PBMCs in the newly recruited cohorts of children one without asthma (control children, n = 7) and the second one with asthma (asthma children, n = 6) at primary school‐age (AGENDAs cohort)." (PMID 33079489, 2020). "In summary, this study just starts to investigate different roles of NFATc1 and NFATc2 in allergic asthma whereby we found that NFATc2 relates more closely to peripheral blood eosinophils and NFATc1 to lymphocyte proliferation in pediatric asthma." (PMID 33079489, 2020). "It is thus possible that NFATc2 correlates with inflammatory eosinophils whereas NFATc1 correlates with lymphocyte proliferation in asthma." (PMID 33079489, 2020). "Moreover, we extended our analysis to NFATc2 which was also found upregulated in different cohorts of children and adults with asthma." (PMID 33079489, 2020). "In this manuscript, we found that NFATc2 mRNA positively correlated with IL‐5 in asthma." (PMID 33079489, 2020). "In addition, in peripheral blood cells, NFATc2 expression was analyzed, in a population of asthmatic children and adults from the Asthma BRIDGE study." (PMID 33079489, 2020). "Moreover, NFATc2 mRNA showed altered expression levels in peripheral blood from 981 children and adults from the Asthma BRIDGE and CAMP cohorts." (PMID 33079489, 2020). "Moreover, NFATc1 directly correlated with lymphocytes number whereas NFATc2 correlated with peripheral eosinophilia in asthma." (PMID 33079489, 2020). "In addition to NFATc1 and NIP45, NFATc2 was found upregulated in asthma." (PMID 33079489, 2020). "Here, we found that NFATc1 mRNA correlated with lymphocytes both in control and asthma and both NFATc1 and NFATc2 mRNA showed a direct correlation with eosinophils in controls but not in asthma, indicating that NFATc1 is associated with lymphocytes and not eosinophils in asthma." (PMID 33079489, 2020). "Moreover, NFATc1 mRNA correlated with lymphocytes both in control and asthma, and NFATC1 and NFATc2 mRNA showed a direct correlation with eosinophils in controls but not in asthma, indicating that NFATc1 is associated with lymphocytes and not eosinophils in asthma." (PMID 33079489, 2020). "In summary, in this paper, we started to analyze the correlation between NFATc1 and NFATc2 in asthma with different cells present in the peripheral blood of children with and without asthma." (PMID 33079489, 2020).
asthma (continued). "In this study, we thus started to investigate the regulation of NFATc2 in the PBMCs in the PreDicta cohorts of preschool children with and without asthma." (PMID 33079489, 2020).
autoimmune disease (4 papers, 2014 to 2025). A disorder resulting from loss of function or tissue destruction of an organ or multiple organs, arising from humoral or cellular immune responses of the individual to their own tissue constituents. "Further studies are needed to assess the potential for selective modulation of Nfatc2, Tob1, or both as part of therapeutic strategies seeking to alter T cell responses in patients with autoimmune diseases and cancer." (PMID 24945807, 2014).
Sepsis (4 papers, 2018 to 2025). Sepsis is defined as life-threatening organ dysfunction caused by a dysregulated host response to infection. "Through bioinformatics approaches, this study successfully identified five genes (IRAK3, S100A9, TXN, NFATC2, and GSTO1) associated with programmed cell death in the context of sepsis." (PMID 40108736, 2025). "The results showed that the expression of IRAK3, S100A9, TXN and GSTO1 in the sepsis group was increased, while the expression of NFATC2 in the sepsis group was decreased (P < 0.05)." (PMID 40108736, 2025). "The NFATC2 was upregulated in sepsis, which was also known as NFAT1, the first member of the nuclear factor of activated T cells (NFAT) family and had an important function in inducing gene transcription during an immune response." (PMID 34938184, 2021). "In order to verify the validity of the diagnostic marker genes, a KS test was performed on the GSE69063 dataset for these five genes, and the results showed that IRAK3, S100A9, TXN and GSTO1 were up-regulated in the sepsis group, while NFATC2 was down-regulated." (PMID 40108736, 2025). "Furthermore, the T-cell receptor signaling pathway was reported to release some activated T cells and nuclear factors, CD4+, CD8+, and NFATC2, to take the immune response in sepsis." (PMID 34938184, 2021). "NFATC2 has been shown to control inflammation and apoptosis, but its role in sepsis has not been reported for now." (PMID 40108736, 2025).
brain injury (3 papers, 2022 to 2026). Acute and chronic (see also brain INJURIES, CHRONIC) injuries to the brain, including the cerebral hemispheres, CEREBELLUM, and brain STEM. "In rats with traumatic brain injury, miR-145-3p regulates the balance between Th1 and Treg cells through the NFATc2/NF-κB axis, thereby reducing inflammation." (PMID 41546098, 2026). "A recent study reported that propofol maintained Th17/Treg cell balance and reduced inflammation in rats with traumatic brain injury via the miR-145-3p/NFATc2/NF-κB axis, proposing a possible regulatory mechanism of propofol in Th17/Treg cell balance." (PMID 36434505, 2022).
cholangiocarcinoma (3 papers, 2024 to 2026). A carcinoma that arises from the intrahepatic biliary tree (intrahepatic cholangiocarcinoma) or from the junction, or adjacent to the junction, of the right and left hepatic ducts (hilar cholangiocarcinoma). "NFATc2 is involved in the cholangiocarcinoma progression via the NEDD4/FBP1 axis." (PMID 39822413, 2024). "Thus, targeting NFATC2 has great therapeutic potential for cholangiocarcinoma." (PMID 38785984, 2024). "Two NFATc2-related axes control cancer progression: the NEDD4/FBP1 axis in cholangiocarcinoma and the MYC/NFATc2 axis in acute myeloid leukemia (AML) cells." (PMID 39822413, 2024).
dementia (3 papers, 2016 to 2023). Loss of intellectual abilities interfering with an individual's social and occupational functions. "NFATc2 was more active in AD patients with mild cognitive impairment, contrary to NFATc4 whose expression was mostly associated with severe dementia." (PMID 27597899, 2016). "In line with that, over-activation of CaN, enhancing nuclear localization of NFATc2 and NFATc4, correlated with increased dementia severity in the human hippocampus, while the subcellular localization of NFATc1 was cytoplasmic." (PMID 38077352, 2023). "Increased NFATc2 activation was revealed in AD patients with mild cognitive impairments, whereas NFATc4 showed a high nuclear accumulation in patients with severe dementia and AD." (PMID 38077352, 2023). "These authors observed increases in calcineurin A activity and more marked shifts of NFATc2 and NFATc4 to nuclear compartments in human hippocampus with increased dementia severity, while even in rapid-autopsy postmortem human brain tissue NFATc1 was unchanged." (PMID 27597899, 2016). "NFATc2 activation is especially critical in the early stages of AD, while selective NFATc4 activation occurs later when the control of neuronal Ca2+ homeostasis and reactive oxidative species production is lost, leading to further neurodegeneration, neuronal death, and ultimately, dementia." (PMID 38077352, 2023). "The accumulation of both CaN and NFATc4 (but not NFATc2) in the nucleus of hippocampal tissue positively correlated with a higher level of soluble Aβ, which steadily increased as the severity of dementia progressed." (PMID 38077352, 2023).
experimental autoimmune encephalomyelitis (3 papers, 2012 to 2018). An autoimmune demyelinating disease of the central nervous system that is produced experimentally in animals by the injection of homogenized brain or spinal cord in Freund's adjuvant. "In experimental autoimmune encephalomyelitis as an animal model of MS, deficiency of Nfatc1 and/or Nfatc2 ameliorated demyelination suggesting that blocking NFAT activity might be a treatment strategy in MS37." (PMID 29500351, 2018). "Interestingly, hyperactivation of NFATC2 in T cells is associated with decreased susceptibility to experimental autoimmune encephalomyelitis, indicating that increased NFATC2 activity may have immunomodulatory effects that down-regulate autoaggressive reactions." (PMID 23092393, 2012).
Obesity (3 papers, 2022 to 2025). Accumulation of substantial excess body fat. "It is well known that a decrease of NFATC2 expression is associated with a reduction of the expression of cytokines in T cells, in particular IL-2, IL-3, IL-4 and TNF-alpha; the latter, in particular, is a pro-inflammatory cytokine associated with obesity and insulin resistance." (PMID 35159548, 2022).
Osteochondroma (3 papers, 2022 to 2024). A common, benign cartiliginous neoplasm arising from the metaphysis of bone. "Recently, Sharma and colleagues identified complete NFAT1 deficiency in a patient with progressive joint contractures, osteochondromas, and B-cell malignancy, caused by a homozygous 4-nucleotide deletion leading a premature stop codon in the NFATC2 gene." (PMID 38427060, 2024).
synucleinopathy (3 papers, 2022 to 2025). A neurodegenerative disease that is characterized by the abnormal accumulation of aggregates of alpha-synuclein protein in neurons, nerve fibers or glial cells. "In a model of synucleinopathy, LRRK2 caused inflammation by promoting a calcineurin-dependent pathway through the phosphorylation of Nuclear Factor of Activated T Cells 2 (NFATc2)." (PMID 36233046, 2022).
acute myeloid leukaemia (2 papers, 2024). "Acute myeloid leukaemia (AML) cells of diverse cytogenetic backgrounds are dependent on NFATC2 for survival; in THP‐1 cells, NFATC2 is downstream of the epigenetic regulator KDM4A." (PMID 38459421, 2024).
Allergy (2 papers, 2019 to 2023). An allergy is an immune response or reaction to substances that are usually not harmful. "The study of infection and allergy in NFATC2 knockout mouse models showed enhanced immune responses, with increased cytokine production in peripheral T-cells." (PMID 31170158, 2019).
dermatofibrosarcoma protuberans (2 papers, 2020 to 2024). Dermatofibrosarcoma protuberans (DFSP) is a rare infiltrating soft tissue sarcoma, generally of low grade malignancy, arising from the dermis of the skin and characteristically associated with a specific chromosomal translocation t(17;22). "The partial amplification pattern might be compatible with fusion of the involved genes, similar to cases described in dermatofibrosarcoma protuberans, with COL1A1::PDGFB or in case of EWSR1::NFATC2 fusion (EWSR1 pattern of FISH) in round cell sarcomas with EWSR1–non-ETS fusions." (PMID 39839837, 2024).
fibrosis (2 papers, 2023 to 2024). the formation of excess fibrous connective tissue in an organ or tissue in a reparative or reactive process. "SIRT3 overexpression alleviates cardiac fibrosis by deacetylating STAT3 and reducing the expression of NFATc2." (PMID 37196115, 2023).
fungal infection (2 papers, 2015 to 2020). "We further found that NFATc2 inhibitor FK506 prevented the upregulation of chemokine CXCL14 induced by paclitaxel, which was in line with the previous finding that inhibition of NFAT signaling decreased the cytokine production during fungal infection." (PMID 33070779, 2020).
heart failure (2 papers, 2014 to 2025). Inability of the heart to pump blood at an adequate rate to meet tissue metabolic requirements. "These four genes CAMTA2, ITGB6, NFATc2, and XDH are all related to heart failure, fibrosis, and cardiovascular disease." (PMID 40181955, 2025).
Hodgkins lymphoma (2 papers, 2021 to 2023). A heterogeneous group of malignant lymphoid neoplasms of B-cell origin characterized histologically by the presence of Hodgkin and Reed-Sternberg (HRS) cells in the vast majority of cases. "The heterozygous germline NFATC2 variant was present in the index case and her mother from Family 1, both diagnosed with Hodgkin’s lymphoma at 46 and 16 years old, respectively." (PMID 36765901, 2023).
mesenchymal neoplasms (2 papers, 2019 to 2025). "Early descriptions of EWSR1::NFATC2-rearranged mesenchymal neoplasms placed them in the category of Ewing-like undifferentiated round cell sarcoma." (PMID 39636306, 2025). "Little is known about the malignant potential of mesenchymal tumors carrying rearrangements of the NFATC2, since even if reported and studied at the molecular level, the more detailed information of clinical course is given only for very few patients." (PMID 31049020, 2019). "The NFATC2 gene is one of the many translocation partners of EWSR1 in gene fusions in a morphologically typical, albeit rare, subgroup of mesenchymal tumors." (PMID 31049020, 2019). "We identified three tumors in our epigenetically distinct METs group that carried fusions described in molecularly defined, non-MET tumor types, i.e., EWSR1::NFATC2-rearranged mesenchymal neoplasms and IRF2BP2::CDX1-rearranged neoplasm." (PMID 39636306, 2025). "This fact seems not to apply to mesenchymal tumors with the involvement of the NFATC2 gene because both in our experience and according to the extensive literature review, they have different properties on the morphological and molecular level." (PMID 31049020, 2019).
skin cutaneous melanoma (2 papers, 2021 to 2024). "A notable exception was higher NFATc2 expression associated with improved PFS in the skin cutaneous melanoma (SKCM) dataset." (PMID 34021224, 2021).
soft tissue tumors (2 papers, 2021 to 2022). "EWSR1/FUS::NFATC2 rearrangements are promiscuous gene fusions found in both benign and malignant bone and soft tissue tumors." (PMID 36555836, 2022).
vascular neoplasm (2 papers, 2021 to 2025). A benign, intermediate, or malignant neoplasm arising from vascular tissue including arteries, veins, venous sinuses, lymphatic vessels, arterioles and capillaries. "We present a case of a woman with a “difficult‐to‐diagnose” multifocal cutaneous vascular neoplasm showing an EWSR1::NFATC2 translocation." (PMID 40037835, 2025). "These analyses identified an EWSR1::NFATC2 translocation, and based on these findings, the lesion was classified as a vascular neoplasm with an NFATC‐related fusion." (PMID 40037835, 2025). "Here, we present a challenging case of a multifocal cutaneous vascular neoplasm, which ultimately revealed an EWSR1::NFATC2 translocation." (PMID 40037835, 2025). "While focal EMA expression was seen in SBC, this was absent in the 3 NFATC2 rearranged vascular tumors." (PMID 34081036, 2021).
acute lymphoblastic leukemia (1 paper, 2021). Leukemia with an acute onset, characterized by the presence of lymphoblasts in the bone marrow and the peripheral blood. "Also, RUNX1 binds to NFATC2 promotor region in CD4 T cell of mouse and human, and Jurkat T cell acute lymphoblastic leukemia cell line." (PMID 35844683, 2021).
acute monocytic leukemia (1 paper, 2014). Acute monoblastic leukemia (AML-M5), is one of the most common subtypes of acute myeloid leukemia (AML) that is either comprised of more than 80% of monoblasts (AML-M5a) or 30-80% monoblasts with (pro)monocytic differentiation (AML-M5b). "Other recent studies have also shown that NFATc2 was expressed in monocyte lineage cells including the murine monocytic cell line RAW264.7 and the human acute monocytic leukemia cell line THP-1, and also in bone marrow–derived macrophages." (PMID 24551078, 2014).
adenoma (1 paper, 2014). A neoplasm arising from the epithelium. "We can speculate that more “adenoma-like” and not “carcinoma-like” molecular profile of these samples could be due to the reduced activity of NFATC2." (PMID 24416320, 2014).
allergic asthma (1 paper, 2020). A asthma with a basis in a pathological type I hypersensitivity reaction. "In addition to NFATc1 and NIP45, also NFATc2 was found upregulated in PBMCs and peripheral blood cells from asthmatic children and adults with allergic asthma." (PMID 33079489, 2020). "In addition, we tried to shed light on the relationship between NFATc1 and NFATc2 and IRF4, another transcription factor upregulating cytokines like IL‐4 and IL‐9 involved in allergic asthma." (PMID 33079489, 2020).
alopecia (1 paper, 2022). Hair loss usually from the scalp. "In the Wnt/Ca2+ signaling pathway, NFATC2 (nuclear factor of activated T cells 2) was up-regulated in giant pandas with alopecia." (PMID 35413801, 2022).
atherosclerosis (1 paper, 2021). A disease characterized by the build-up of fatty material and calcium deposition in the arterial wall resulting in partial or complete occlusion of the arterial lumen. "Overexpression of NFATc1 and NFATc2 causes Egr-3 upregulation and the excessive activation of endothelial cells, which might lead to vascular disease, such as pathological angiogenesis, inflammation, and atherosclerosis." (PMID 33791348, 2021).
Autoimmunity (1 paper, 2025). The occurrence of an immune reaction against the organism's own cells or tissues. "NFATC2 is involved in controlling the balance between effector T cells, which are responsible for attacking pathogens, and regulatory T cells, which help prevent autoimmunity." (PMID 40085692, 2025).
B cell lymphopenia (1 paper, 2019). "The severe B cell lymphopenia observed in the absence of NFATc1 activity was not present in mice that were deficient in NFATc2, NFATc3, or both." (PMID 29907883, 2019).
breast adenocarcinoma (1 paper, 2019). "Current annotations of 2RQ, 7 PA, and 7PL missense mutations within the NFATc2 PxIxIT site recovered from sequenced lung and breast adenocarcinomas describe them as unlikely to have functional effects in vivo (cBioPortal, 2018)." (PMID 31282865, 2019).
chronic obstructive pulmonary disease (1 paper, 2017). A chronic and progressive lung disorder characterized by the loss of elasticity of the bronchial tree and the air sacs, destruction of the air sacs wall, thickening of the bronchial wall, and mucous accumulation in the bronchial tree. "While many studies modeling carcinogenetic mechanisms of tobacco toxicity or chronic obstructive pulmonary diseases have featured the NF-κB pathway as a major mediator, our findings on the effects of NFATc2 on TIC induction might add to this repertoire." (PMID 28737489, 2017).